SP1 (Sp1 transcription factor)
Diseases named in the same sentence as SP1 in open-access papers (continued):
Sharing a sentence is not in itself a finding about the gene and the disease.
tumor (continued). "High Sp1 levels often predict poor prognosis; therefore, researchers have identified Sp1 as a tumor marker." (PMID 39228402, 2024). "Significant differences were observed for the SP1 gene in different subgroups of the patient’s tumor and normal tissues (p < 0.05)." (PMID 38540340, 2024). "Real-time PCR and western blot analyses manifested a significant elevation of Sp1 expression in response to tumor infiltration treatment on POD 6, 12, and 18 within DRG." (PMID 39448865, 2024). "Multiple SP1 binding sites were identified within the promoter region of the Xpo1 gene and, through these sites, SP1 can regulate Xpo1/Crm1 transcription in transformed tumor cells." (PMID 38336745, 2024). "In mitophagy pathway, a total of seven proteins belonged to Stage I unique up-regulated proteins, among which TFEB, BNIP3L and SP1 were either statistical significantly up-regulated in Stage I when compared to middle and late stage tumor groups." (PMID 38182978, 2024). "Depletion of SAT1 or pharmacological inhibition of the transcriptional regulator SP1 using mithramycin in orthotopic tumour mouse models diminishes stromal cell-induced metabolic reprogramming and tumour burden." (PMID 38429478, 2024). "For example, Sp1 can maintain the continuous tumor proliferation signal by mediating the transcription of epidermal growth factor and its receptor, fibroblast growth factor, insulin-like growth factor, and its receptor." (PMID 39228402, 2024). "Invasion and proliferation of tumor cells are mediated by activation of ERK kinase through Sp1 modification." (PMID 39228402, 2024). "We observed a significant increase in SP1 in acidic regions in tumour tissue compared to tumour regions at physiological pH." (PMID 38429478, 2024). "Collectively, SP1 facilitated the proliferation of tumor cells and glycolysis in the cells by activating RBBP7, thereby influencing PI3K/AKT signaling." (PMID 38368381, 2024). "Our previous study revealed that HIF1α collaborates with SP1 to regulate the cyclization of circ_0001875 in a hypoxic tumor microenvironment." (PMID 39030638, 2024). "In this study, we provide preliminary evidence that tumor infiltration leads to an upregulation of GPR160 expression through Sp1-mediated activation in injured DRG neurons." (PMID 39448865, 2024). "Overexpression of Sp1 is involved in tumor progression or metastasis via regulation of the expression of Sp1-responsive genes related to cell growth, apoptosis, and angiogenesis." (PMID 38284882, 2024). "SP1 expression is higher in tumor tissues than in normal tissues, and the protein levels of SP1 have a positive correlation with HIF1A-AS2 levels, demonstrating that SP1 transcriptionally activates HIF1A-AS2." (PMID 39227375, 2024). "In this study of tamoxifen-inducible CreERT2-mediated deletion of endothelial Sp1/Sp3 mice, the loss of Sp1/Sp3 delayed the angiogenesis in neonatal retinas, reparative angiogenesis to HLI and skin wound, even the angiogenesis in the subcutaneous tumor." (PMID 36759621, 2023). "As reported in a previous study, aberrant expression and activation of SP1 protein in tumor tissues regulate tumor proliferation, angiogenesis, and metastatic ability." (PMID 36744249, 2023). "Endothelial-specific Sp1/Sp3 knockout reduces angiogenesis in retinal, pathological, and tumor models and induced activation of the Notch1 pathway." (PMID 36759621, 2023). "Further analysis of the CCL5/Sp1/CD44 axis in EpCAM+ cells revealed that this signaling pathway was more activated in advanced tumor stages, which was consistent with the protein analysis." (PMID 37553567, 2023). "Accumulating evidence suggests that specificity protein 1 (Sp1) plays a pivotal role in tumour progression." (PMID 37147632, 2023). "ADEM10, EPHB2, HDAC4, and SEPP1 in CRC inhibit cell migration, invasion, tumor growth, and liver metastasis through the SP1." (PMID 36798788, 2023).
tumor (continued). "We previously demonstrated that Sp1, an established target of the tumor suppressor miR-29b, negatively impacts miR-29b expression acting in the context of an actionable transcriptional feedback loop in MM." (PMID 37759449, 2023). "SP1 is reported to undergo proteasome-dependent or -independent degradation according to the different tumor cell type." (PMID 37627542, 2023). "Inosine elevation further induces Rag GTPases abundance and mTORC1 signaling pathway by enhancing transcription factor SP1 level in the starved tumor." (PMID 37532694, 2023). "eEF2 and phosphorylated eEF2 are prognostic indicators of HCC patient survival, and that eEF2 kinase promotes HCC angiogenesis and tumor progression through SP1/KLF5-mediated VEGF expression." (PMID 37740172, 2023). "Thiazolidinedione (TZD) inhibits FOXM1 expression through the downregulation of SP1, negatively regulating tumor cell growth and promoting apoptosis." (PMID 36661515, 2023). "We used the target genes of SP1 from DoRothEA33 to infer the SP1 activities in ccRCC tumor using VIPER34." (PMID 37460463, 2023). "At present, there is strong evidence for the role of Sp1 in inducing stemness, and the cooperating factors vary with tumor type." (PMID 36982239, 2023). "Consistent with this, numerous TUNEL-positive apoptotic cells were observed in the tumor tissues from the si-Sp1 + IR group, and their number was approximately 35% higher than that in the NC + X-ray group." (PMID 37445835, 2023). "The immunohistochemical analysis of the tumor tissues also showed a remarkable increase in the expression of Sp1 protein on day five post-irradiation." (PMID 37445835, 2023). "A dysregulated Sp1/miR-130b-3p/HOXA5 axis has been suggested to contribute to tumor angiogenesis and the progression of LIHC." (PMID 37240447, 2023). "The knockdown of Sp1 significantly increased the inhibitory effects of IR on tumor growth compared to Sp1 knockdown or IR alone, which was consistent with the in vitro findings." (PMID 37445835, 2023). "SP1 also contributes to the malignant phenotype by regulating oncogenes that influence tumor cell proliferation, invasion and metastasis." (PMID 37894370, 2023). "AGEs caused an increase in pERK and MEK1/2 inhibitor-induced reduction of this phosphorylation led to suppression of the Sp1 expression, suggesting the involvement of the RAGE/ERK/Sp1/MMP2 pathway in AGE-induced tumor invasion and metastasis." (PMID 36677584, 2023). "Remarkably, the knockdown of SP1 inhibited the Rag GTPases and mTORC1 pathway in TC more than that in control tumor-bearing mice." (PMID 37532694, 2023). "Specificity protein 1 (Sp1) is a transcriptional factor regulating the essential genes involved with cell proliferation and metastasis of various human neoplasms." (PMID 37373974, 2023). "Both the weight and the volume of the tumours were increased after Sp1 overexpression but were reduced by Sp1 knockdown when compared with the control group." (PMID 37147632, 2023). "Inhibition of Sp1 can overcome this resistance in vitro and in vivo for different tumor entities, including lung and urothelial cancer." (PMID 36843002, 2023). "There are one AP1 element and two SP1 elements that contributed to constitutive and tumor promoter-induced promoter activity of NRP1 in HeLa cells." (PMID 35600336, 2022). "Accordingly, we detected and observed an obvious upregulation of E2F7 in both HCC tumor tissues and cells, positively correlated with SP1, SOX4, and Anillin." (PMID 35924788, 2022). "ZBTB10 serves as a transcriptional inhibitor of SP1 transcription factors and participates in inhibiting tumor activities, including tumor growth, chemoresistance, and migration/invasion, suggesting that ZBTB10 should be considered a tumor suppressor." (PMID 35306527, 2022). "Tumor cell-derived GM-CSF increased the expression of FcγRIIB on MDSCs, along with enhanced differentiation of MDSCs from HPCs by activating the Sp1 signaling." (PMID 34976216, 2022).
tumor (continued). "Compared with that in adjacent normal tissues, Sp1/Sp3 protein expression levels were also significantly higher in tumor tissues." (PMID 35982909, 2022). "It is well known that some transcription factors are responsible for the transcription activity of uPA in various tumor cells, such as Sp1, AP1 and HOXA5." (PMID 36612038, 2022). "TMPRSS4 promoted tumor cell proliferation and metastasis by inducing specificity protein 1/3 (Sp1/3), activator protein-1 (AP-1), and NF-κB transcription factors." (PMID 36076996, 2022). "The abnormal activation of SP1 upregulates the expression of tumor-related factors and promotes the proliferation and metastasis of colon, gastric, and pancreatic tumors." (PMID 35774082, 2022). "Lastly, we performed xenograft tumor in nude mice to evaluate the effect of SP1 on the tumorigenesis of CRC cells in vivo through regulation of the TUG1/miR-421/KDM2A/ERK pathway." (PMID 35508523, 2022). "Among thesescreened transcriptional factors, Sp1 was over-expressed in most tumor cells and tissues." (PMID 35778451, 2022). "SP1 was identified as a common transcription factor that is dysregulated in many tumor types and contributes to tumor proliferation and metastasis." (PMID 35957833, 2022). "The abundance of SP1, an important transcription factor, is typically increased in most tumors, and SP1 participates in tumor cell proliferation, differentiation, DNA damage response, apoptosis, senescence, and angiogenesis." (PMID 36213324, 2022). "Oncogenic STRAP inhibits E-cadherin and P21(CIP1) through modulation of transcription factor SP1, contributing to tumor progression." (PMID 36551208, 2022). "The circ-0001875/miR-31-5p/SP1 axis is correlated with tumor clinical features and prognosis of NSCLC patients." (PMID 35473752, 2022). "Taken together, these results indicate that blockade of Sp1 is an efficient anti-tumor approach via reducing FcγRIIB-mediated accumulation and immunosuppressive activity of MDSCs in the TME." (PMID 34976216, 2022). "Our results suggest that in the context of tumor cell cultures, SP1 shows a more relevant role than NFY in driving PNPT1 expression." (PMID 36232701, 2022). "Sp1 is overexpressed in most tumours and can inhibit RECK transcription by binding to its promoter region." (PMID 35892136, 2022). "Another factor behind TMZ resistance has been attributed to the specificity protein 1 (Sp1), which reportedly encourages the development of drug resistance in GB by regulating cell senescence, DNA damage response, and tumor angiogenesis, among others." (PMID 36613792, 2022). "The tumor supernatants and treatment with GM-CSF also significantly upregulated the expression of Sp1." (PMID 34976216, 2022). "In particular, SP1 can form an autoregulatory feedback loop with certain microRNAs and participate in the regulation of tumor progression as a whole." (PMID 34905435, 2021). "Specificity Protein 1 (SP1) is the most representative member of the tumor-related transcription factors." (PMID 33731131, 2021). "One of the best described anti-tumour mechanisms of action for MTM is their ability to inhibit the expression of the pleiotropic SP1 transcription factor and its downstream signaling." (PMID 34488783, 2021). "AP-1 factors and STAT3 are particularly important for transformation in our model, and loss of ETS, KLF/SP1, THAP11, CREB, ZBTB33, or CEBP inhibits transformation or tumor growth in other cellular or animal models." (PMID 33523865, 2021).
tumor (continued). "Oral administration of SP1 suppressed microvessel density formation in BALB/c nude mice tumour tissues, decreased serum MMP-2, and downregulated the expression of HIF-1α and VEGF, suggesting the promising inhibitory effect of SP1 on angiogenesis." (PMID 33669877, 2021). "SP-1 is a nuclear transcription factor and regulates tumor proliferation, migration, angiogenesis, and invasion." (PMID 34055778, 2021). "Subsequently, miR-125b-5p downregulation induces specificity protein 1 (Sp1)-mediated activation of CD248 that does trigger not only tumor cells metastases but also 5-FU chemoresistance." (PMID 34571731, 2021). "Sp1 is involved in the modulation of the activities of the occludin promoter by Krüpple-like factor 4 in the blood-tumor barrier." (PMID 33827415, 2021). "miR-363 mimic contributed to a decline in tumor weight, while overexpression of circ0005654 and sp1 increased the tumor weight again." (PMID 34499009, 2021). "SP1, a key member of the transcription factor SP family, plays important roles in tissue development, cell differentiation, and tumor molecular biology." (PMID 34745421, 2021). "Here, we describe a new signaling axis, involving EGFR, miR‐9, KLF5, and Sp1, that connects the tumor stem‐like features of HNSCC with the response to therapy." (PMID 34062049, 2021). "In tumor tissues from mice, we also found that overexpression of circ0005654 and sp1 was able to re-activate the Wnt/β-catenin pathway that was blocked due to overexpression of miR-363." (PMID 34499009, 2021). "It is interesting to note that Sp1 expression was found high also in Hh-dependent MB tumor cells, while KCASH2 expression was reduced in MB cells." (PMID 33898425, 2021). "Then, we verified protein levels of Sp1 in mouse tumors, which showed similar change trends in tumor size and growth rate." (PMID 34145213, 2021). "In summary, these data elucidated that SNHG6 was regulated by SP1 on the transcriptional level and was involved in the tumor-promoting effect of SP1." (PMID 33431838, 2021). "An in vivo tumorigenesis experiment was used to evaluate the effect of SP1 knockdown on tumor growth and protein levels were evaluated by immunohistochemistry." (PMID 34905435, 2021). "Previous studies demonstrated that overexpression of SP1 promoted cell proliferation and tumour growth." (PMID 33579314, 2021). "In conclusion, the overexpression of LAMC1, upregulated by TGFβ1 via SMAD4/SP1 synergistic activation, promoted the proliferation and migration of tumor cells mainly via NF‐κB/MMP9‐MMP14." (PMID 34218518, 2021). "Rescue of SP1 expression in CRC cells partly abrogated miR-320a-induced inhibition of cell behaviors, indicating that miR-320a exerts a tumor-suppressive role at least partly by inhibiting SP1 activity." (PMID 33731131, 2021). "Regulatory relationships between TFs and miRNAs have been reported, such as a recently identified SP1/miR-22 feedback loop in CRC that facilitates tumor progression by suppressing downstream PTEN/AKT signaling." (PMID 33731131, 2021). "Previous studies disclosed that SP1 can transcriptionally regulate miRNAs and coding genes to facilitate tumor progression." (PMID 33731131, 2021). "EGR1 is a direct regulator of many tumor suppressor genes, also SP TF family members (SP1 and SP2) are involved in gene regulation in tumors." (PMID 34282050, 2021). "As a member of the Sp/KLF family, the transcription factor specificity protein 1 (Sp1) is involved in regulating the expression of genes related to tumor progression-related signal pathways." (PMID 33472586, 2021).
tumor (continued). "Previous studies reported that as an TF, SP1 regulates tumor-related miRNAs expression during tumorigenesis, which is a crucial aspect of SP1-dominated tumor modulatory mechanisms." (PMID 33731131, 2021). "Mechanistically, by targeting KLF5, miR‐9 regulates the expression of the transcription factor Sp1 that, in turn, stimulates tumor growth and confers resistance to RT+CTX in vitro and in vivo." (PMID 34062049, 2021). "Taken together, these results indicated that downregulated Sp1 inhibited tumor progression and that miR-2110 downregulation reversed the Sp1 silencing-induced phenotype of TNBC cells." (PMID 34145213, 2021). "Adjacent normal tissues had a lower level of SP1 (OR = 0.15; 95%CI:0.08-0.31; p < 0.05) in comparison with tumor sites." (PMID 34257529, 2021). "We further validated SP1 expression on the protein level, and the differential protein expression between tumor and normal samples was significant in LIHC (Wilcoxon Signed Rank test, P = 4.14e-13)." (PMID 33488678, 2020). "An earlier study noted that TA has positive effects on OC tumor growth in mice, including degradation of the Sp1 protein, leading to a decrease in cell proliferation, while encouraging apoptosis and cell cycle arrest." (PMID 32050495, 2020). "Decreased TRIM25 expression and increased SP1 expression in tumor tissues were positively correlated with poor prognosis of GC patients." (PMID 32576271, 2020). "Investigations have revealed that both upregulation and downregulation of Sp1 can modulate several oncogenes, thus regulating the metastasis and tumor growth in OC." (PMID 32050495, 2020). "Recently, it has been reported that targeting Sp1 expression at the G2/M phase of cell cycle by radiotherapy helps reduce tumor development." (PMID 32050495, 2020). "In summary, our study certificated that miR-181b functioned as a tumor suppressor by directly targeting SP1 to prevent glucose metabolism and cell proliferation." (PMID 32158359, 2020). "SP1 is selected as a candidate driver gene only by our method (ranked top three), and SP1 RNA and protein differential expression between tumor and normal samples are statistically significant in liver hepatocellular carcinoma." (PMID 33488678, 2020). "Our findings highlight the importance of Sp1/miR-130b-3p/HOXA5 axis in tumor angiogenesis and recurrence, and implicate HOXA5 as a potential target for HCC treatment." (PMID 32373208, 2020). "Transcription factor Sp1 has been extensively reported to increase expression of many oncogenes, thereby promoting the progression of OS and other types of tumour." (PMID 32743904, 2020). "Sp1 was the first cloned and purified nuclear transcription factor, and it plays an important role in tumor growth, metastasis and angiogenesis by regulating downstream target genes, and is highly expressed in PDAC and associated with poor prognosis." (PMID 33299646, 2020). "SP1 is the biomarker for tumor stratification in TCGA-STAD and TCGA-BLCA, and SP1 RNA expression is associated with survival outcome in TCGA-STAD dataset (Cox proportional hazards model, P = 0.02)." (PMID 33488678, 2020). "Regardless, more experiments and statistical analysis are required to further determine the critical role and correlations of CCAT1, miR7‐5p and SP1, and tumor sizes in this process in mice model." (PMID 31823440, 2020). "Further, the OS data showed the patients with low TRIM25 or high SP1 expression alone in GC tumor tissues had poor OS than high TRIM25 or low SP1 ones." (PMID 32576271, 2020).